PRR14 (proline rich 14)
Description:
Functions in tethering peripheral heterochromatin to the nuclear lamina during interphase, possibly through the interaction with heterochromatin protein CBX5/HP1 alpha. Might play a role in reattaching heterochromatin to the nuclear lamina at mitotic exit. Promotes myoblast differentiation during skeletal myogenesis, possibly by stimulating transcription factor MyoD activity via binding to CBX5/HP1 alpha. Involved in the positive regulation of the PI3K-Akt-mTOR signaling pathway and in promoting cell proliferation, possibly via binding to GRB2.
Synonyms: MGC3121
Tractability: PROTAC: ubiquitination databases record sites on it.
Gene: Protein-coding gene on chromosome 16 (30,650,717 to 30,656,413, forward strand). Ensembl gene ENSG00000156858.
Subcellular location: Chromosome; Nucleus; Nucleus lamina; Nucleus, nucleoplasm
Subcellular location (Human Protein Atlas): Nucleoplasm
Gene Ontology:
Molecular function: protein binding
Cellular component: chromosome; nuclear lamina; nucleoplasm; nucleus
Genetic constraint (gnomAD): Loss-of-function variants: 33 observed, 57.44 expected, observed/expected ratio (o/e) 0.57, 90% interval 0.43 to 0.77. The upper end of that interval is the gene's LOEUF score, 0.77, which puts it in group 3 of 6, group 1 being the genes least tolerant of losing a copy. Missense variants: 715 observed, 797.85 expected, observed/expected ratio (o/e) 0.9, 90% interval 0.84 to 0.95. Synonymous variants: 302 observed, 321.81 expected, observed/expected ratio (o/e) 0.94, 90% interval 0.85 to 1.03.
Homologues: Orthologues: chimpanzee PRR14 (99% identical), macaque PRR14 (88% identical), dog PRR14 (84% identical), pig PRR14 (84% identical), rabbit PRR14 (81% identical), mouse Prr14 (76% identical), rat Prr14 (75% identical), tropical clawed frog prr14 (24% identical), zebrafish prr14 (21% identical). Paralogues in human: PRR14L (23% identical).